AIFM2 (AIF family member 2, ferroptosis suppressor)
Diseases named in the same sentence as AIFM2 in open-access papers (continued):
Sharing a sentence is not in itself a finding about the gene and the disease.
cancer (48 papers, 2011 to 2026). A tumor composed of atypical neoplastic, often pleomorphic cells that invade other tissues. "A number of point mutations in the AIFM2 gene are present as somatic mutations in people with cancer, including those encoding p.G244D, p.E160D, pE160 stop, p.K355R and p.D285N." (PMID 37957306, 2023). "FSP1 (AIFM2) upregulation in KRAS-mutant cancer cells has been linked to ferroptosis resistance." (PMID 37371948, 2023). "Initially identified as a positive regulator of mitochondrial apoptosis, AIFM2 translocates from mitochondria to the plasma membrane in GPX4-low-expressing cancer cells when stimulated with ferroptosis inducers (e.g., RSL3 and ML162)." (PMID 38844964, 2024). "There is a positive correlation between AIFM2 expression and the sensitivity of cancer cells to ferroptosis inducers such as RSL3, ML162, ML210, and erastin." (PMID 39534872, 2024). "Abnormal expression of SLC7A11, GPX4, and AIFM2 was found in a variety of tumors, which can be used to evaluate the prognosis and invasion degree of various cancers." (PMID 37894808, 2023). "Remarkably, it has been reported that AIFM2 protects cancer cells from erastin-, sorafenib-, and RSL3-induced ferroptosis via an approach independent of ubiquinol." (PMID 35911966, 2022). "Apoptosis-inducing factor mitochondria-associated 2 (AIFM2)-dependent ESCRT-III recruitment regulates membrane budding, fission, and repair and blocks erastin- and RSL3-induced ferroptotic cancer cell death, which is responsible for ferroptosis resistance." (PMID 36330465, 2022). "Our research group has shown that 4-HNE activates mitochondria apoptosis-inducing factor (AIFM2) translocation and facilitates apoptosis in mice and human heart tissue during anti-cancer treatment." (PMID 36358905, 2022). "We also analyzed the prognostic values of SLC7A11, GPX4, and AIFM2 in pan-cancer using Kaplan–Meier database." (PMID 34722530, 2021). "In human lung cancer cell lines, the activation of AIFM2 markedly contributed to cancer cells apoptosis undergoing exogenous toxicological stimulus." (PMID 34945503, 2021). "We further investigated the relationships between the expression levels of SLC7A11, GPX4, and AIFM2 and immune infiltration levels in pan-cancer by using the TIMER database." (PMID 34722530, 2021). "Next, we analyzed the prognostic values of SLC7A11, GPX4, and AIFM2 in pan-cancer using GEPIA database." (PMID 34722530, 2021). "In summary, SLC7A11, GPX4, and AIFM2 are dysregulated in many types of cancers, and are candidate prognostic biomarkers for many types of cancers, and can be used to evaluate the infiltration of immune cells in tumor tissues." (PMID 34722530, 2021). "Our results suggest that SLC7A11, GPX4, and AIFM2 are dysregulated in many types of cancers, and are candidate prognostic biomarkers for many types of cancers, and can be used to evaluate the infiltration of immune cells in tumor tissues." (PMID 34722530, 2021). "In human breast 33, gastric 34 and lung 35 cancer cells, apoptosis is mediated by the upregulation of AIFM2 expression and accumulation of AIFM2 in the mitochondria." (PMID 32724472, 2020). "It has been reported that AIFM2 has a pro-apoptotic function and that its expression is down-regulated in cancer cell lines by comparison with normal cell lines." (PMID 21943319, 2011). "Indeed, LDHB gene expression negatively correlated with the expression of AIFM2, which encodes FSP1, in the Cancer Cell Line Encyclopedia and also in the 10967 samples included in the TCGA PanCancer Atlas." (PMID 40090955, 2025). "This relationship suggests that targeting AIFM2 could be a promising strategy to overcome ferroptosis resistance in cancer therapy, particularly in tumors that are resistant to conventional treatments." (PMID 39534872, 2024). "However, the role of AIFM2 in regulating the development and progression of human cancers remains largely unexplored, especially in HCC." (PMID 37735151, 2023).
cancer (continued). "Accumulating evidence has revealed that alterations in NAD+ homeostasis are closely associated with many age-related diseases, including cancer, implying that AIFM2 may play a role in human cancer." (PMID 37735151, 2023). "In summary,AIFM2 expression may have little effect on cancer progression and survival, which may be explained by the complex functions of AIFM2, including the induction of apoptosis and suppression of ferroptosis." (PMID 37140233, 2023). "We also analyzed the mRNA levels of SLC7A11, GPX4, and AIFM2 in pan-cancer using Oncomime database." (PMID 34722530, 2021). "Prognostic values of SLC7A11, GPX4, and AIFM2 in pan-cancer in Kaplan–Meier database." (PMID 34722530, 2021). "In addition to AIFM2 and NFS1, the remaining seven genes in the signature were also associated with cancer in both basic and clinical research fields." (PMID 34778244, 2021). "Furthermore, the ferroptosis suppressor protein 1 (FSP1/AIFM2) controls the generation of reduced CoQ10, and can also inhibit ferroptosis in cancer cells by activating the ESCRT-III membrane repair system." (PMID 34796174, 2021). "Additionally, the AIFM2 gene, a gene with pro-apoptotic function and often being down-regulated in various cancers was indeed significantly decreased in spleen of the line 72 infected birds." (PMID 31252692, 2019). "Modulating AIFM2 function could offerstrategies for treating therapy-resistant cancers." (PMID 41552592, 2026). "However, the role of AIFM2 in the progression of human cancers remains largely unexplored." (PMID 37735151, 2023). "ACSL3, AIFM2, HSD17B7, LPCAT1, LSS, PLIN3 and RAB10 were up-regulated with the progression of cancer stage of HCC patients, while CIDEB, G0S2, HSD17B13, PLIN1 and PLIN2 were down-regulated." (PMID 37464334, 2023). "Based on function, the 12 FRGs can be grouped into four classes: Lipid metabolism (GPX4, LPCAT3, ACSL5, and ACSL6), antioxidant metabolism (CD44, SESN2, and AIFM2), iron metabolism (CISD1 and HSPB1), and cancer metabolism (SOCS1, FH, and G3BP1)." (PMID 34784264, 2022). "The 12 FRGs are divided into 4 categories according to their functions: lipid metabolism (GPX4, LPCAT3, ACSL5, ACSL6), antioxidant (CD44, SESN2, AIFM2), iron metabolism (CISD1, HSPB1), and cancer metabolism (SOCS1, FH, G3BP1)." (PMID 35559049, 2022). "Furthermore, targeting regulators of ferroptosis, such as AIFM2, glutathione synthetase (GSS), GPX4, FA complementation group D2 (FANCD2), and MAF BZIP transcription factor F (MAFF) can sensitize specific cancers to radiotherapy-dependent ferroptosis." (PMID 38844964, 2024). "Another key pathway parallel to GPX4 is the AIFM2-CoQ10 axis, and ferroptosis sensitizer 1 (FSEN1) can noncompetitively target AIFM2 to sensitize cancer cells to ferroptosis." (PMID 38844964, 2024). "While studies across various cancers have highlighted the efficacy of ferroptosis induction, particularly by inhibiting GPX4 and AIFM2, in eliminating apoptosis-resistant cancer cells, the exploration of ferroptosis in the context of AML remains relatively limited." (PMID 38032290, 2023). "FSP1 is expressed in numerous cancer cell lines, and knockout of the FSP1-encoding gene, apoptosis-inducing factor mitochondria associated 2 (Aifm2), has no impact on embryo development and does not cause any overt phenotype in adult mice." (PMID 37957306, 2023). "In addition to this GSH-dependent route of ferroptosis protection, the COQ10 oxidoreductase ferroptosis suppressor protein 1 (FSP1, formerly AIFM2) protects cancer cell lines of various tissue origins from ferroptosis through the generation of the lipid radical-trapping agent ubiquinole." (PMID 41173858, 2025). "Compounds MJ2, MJ8, MJ15, and MJ19 had a stronger effect on the expression of the BCL2, MDM2, AIFM2, IL6, and IL8 genes in the healthy BEAS-2B cell line than in the cancerous HCT116 cell line, which may indicate their potential protective effect on normal cells with limited effect on cancer cells." (PMID 40725171, 2025).
cancer (continued). "However, cells lacking both AIFM2 and NQO1 exhibit increased sensitivity compared to AIFM2 knockout U-2 OS cancer cells." (PMID 39534872, 2024).
tumor (42 papers, 2018 to 2026). "In certain types of cancer, such as cervical cancer and hepatocellular carcinoma, the expression levels of AIFM2 have been associated with a reduction in tumor formation." (PMID 39397802, 2024). "AIFM2 expression is positively associated with the clinicopathological feature of tumor metastasis in patients with HCC." (PMID 37735151, 2023). "Further research is needed to elucidate the precise mechanisms underlying AIFM2’s function, particularly in the context of naturally occurring mutations and their implications in ferroptosis and tumor biology." (PMID 37371948, 2023). "We observed that high expression levels of GPX4 and AIFM2 were significantly associated with tumor purity in ESCA (R = 0.25, p = 6.93e-04; R = 0.279, p = 1.43e-04) and in HNSC, respectively (R = 0.223, p = 5.37e-07; R = 0.205, p = 4.41e-06)." (PMID 34722530, 2021). "By analyzing the gene expression data of immune markers in the TIMER database, we investigated the association between the levels of SLC7A11, GPX4, and AIFM2 and the status of tumor-infiltrating immune cells in ESCA, HNSC, COAD, READ, STAD, and LUAD." (PMID 34722530, 2021). "The six‐gene diagnostic model (AIFM2, ABCG1, LIPG, DGAT2, LPCAT1, and VCP) demonstrated near‐perfect classification of tumor versus normal tissues (AUC ≈0.99 in ROC analysis; 99.8% accuracy in SVM analysis)." (PMID 40804485, 2025). "Concurrently, in vivo experiments have shown that knocking down IGF2BP1 or AIFM2 can effectively suppress tumor growth and metastasis." (PMID 40386780, 2025). "A significant upregulation of AIFM2 at both mRNA and protein levels was observed in tumor tissues of HCC as compared with normal liver tissues." (PMID 37735151, 2023). "Significant upregulation of AIFM2 in tumor tissues of HCC promoted us to investigate the potential oncogenic functions of AIFM2 in HCC progression." (PMID 37735151, 2023). "In line with the in vitro findings, in vivo, lung metastasis nude mouse models also demonstrated that AIFM2 upregulation significantly increased the metastatic tumor nodules formed in the lungs." (PMID 37735151, 2023). "As expected, a significant positive correlation was found in tumor tissues of HCC between the expressions of AIFM2 and PGC-1α at the protein level, as evaluated by IHC staining assay." (PMID 37735151, 2023). "SESN2 and AIFM2 are responsible for tumor cell survival, but their exact functions in AML cells ferroptosis remains uncharacterized." (PMID 34784264, 2022). "In summary, five of the genes (CARS1, CHAC1, FANCD2, G6PD, and HMOX1) in the prognostic model have been reported to contribute to ferroptosis and to be upregulated in BC tumor tissue, in contrast to AIFM2." (PMID 36313179, 2022). "The expression of AIFM2 was lower in tumor tissues than in normal tissues, but the high expression of AIFM2 tended to have higher GS (p < 0.01)." (PMID 34778244, 2021). "Targeting ferroptosis-related genes such as GPX4, AIFM2, and HDAC can modulate oxidative stress and thus confer susceptibility to ferroptosis in tumor cells." (PMID 35360452, 2021). "This suggested that GPX4 and AIFM2 played important roles in regulating tumor immunity by affecting the ferroptosis of B cell, CD8+ T cell, and CD4+ T cell in HNSC." (PMID 34722530, 2021). "The results of a meta-analysis after combining 15 independent datasets showed that the expression of AIFM2 in the tumor was lower than that in normal tissues, while opposite results were obtained in NFS1 (p < 0.001)." (PMID 34778244, 2021). "AIFM2 protects tumor cells by catalyzing the continuous regeneration of CoQ10 and improving the ability to trap lipid peroxyl radicals to inhibit ferroptosis." (PMID 34778244, 2021). "Blocking AIFM2 strongly sensitized tumor cells to ferroptosis and could be developed as a promising antitumor method." (PMID 40002690, 2025). "Moreover, tumor cells that overexpress AIFM2 provide significant protection against both pharmacological and genetic induction of ferroptosis." (PMID 40248093, 2025).
tumor (continued). "In BC, the mechanism of action of AIFM2 exhibits subtype-specific differences, with its overexpression promoting tumor cell proliferation, invasion and migration; Genome-wide analysis indicates that upregulation of AIFM2 affects BC cell proliferation and patient prognosis." (PMID 41415282, 2025). "Notably, we identified Apoptosis-Inducing Factor Mitochondria Associated 2 (AIFM2) and Glutathione Peroxidase 4 (GPX4), pivotal regulators of tumor ferroptosis, as direct targets of miR-6805." (PMID 38244593, 2024). "Correlation analysis indicated a significant positive correlation between the expression of AIFM2 and clinicopathological feature of tumor metastasis, implying that AIFM2 may play an oncogenic role in HCC progression." (PMID 37735151, 2023). "Moreover, in line with the expression of AIFM2 in tumor tissues of HCC, a significant increase in AIFM2 expression was also observed in HCC cell lines as compared to normal hepatocytes by using qRT-PCR and western blot analysis." (PMID 37735151, 2023). "However, recent studies raise concerns about the pro-tumor growth role of AIFM2 in promoting aerobic glycolysis." (PMID 37371948, 2023). "Although a previous study reported that GPX4 could prevent Treg cells from lipid peroxidation and ferroptosis, whether SLC7A11, GPX4, and AIFM2 participated in the regulation of ferroptosis of other immune cells and tumor progression is still largely unknown." (PMID 34722530, 2021). "However, the expression of AIFM2 in tumor tissues remains largely unknown." (PMID 37735151, 2023). "In summary, we demonstrate that AIFM2 is frequently overexpressed in HCC and plays a crucial role in the promotion of tumor metastasis by increasing mitochondrial biogenesis and oxidative phosphorylation through activation of NAD+/SIRT1/PGC-1α signaling." (PMID 37735151, 2023). "A recent study has revealed a potential relationship between AIFM2 and EBF3, which acts as a tumor suppressor gene in AML." (PMID 36338716, 2022). "First, we evaluated the differential expression of AIFM2 and NFS1 between the tumor tissues and corresponding normal tissues in multiple datasets." (PMID 34778244, 2021). "The results showed that the expression of SP1, KEAP1, AIFM2, and NOX4 all increased in tumor tissues." (PMID 34745421, 2021). "Recent research has also shown elevated levels of AIFM2 in KRAS mutant tumors versus non-tumorous tissue, with elevated levels linked to tumor initiation and ferroptosis resistance." (PMID 39617061, 2025). "While LPCAT1, AIFM2, and VCP have not been directly validated as diagnostic biomarkers, they are functionally implicated in tumor pathogenesis." (PMID 40804485, 2025). "We also determined the methylation level of AIFM2 in 8-paired tumor and adjacent non-tumor tissues using methylation-specific PCR." (PMID 37735151, 2023). "We observed obviously decreased methylation level of AIFM2 in tumor tissues of HCC, as compared with non-tumor tissues." (PMID 37735151, 2023). "Interestingly, AIFM2 and GPX4 have been determined as vital regulators of tumor cell ferroptosis." (PMID 38244593, 2024).
infection (7 papers, 2010 to 2025). The state of being infected such as from the introduction of a foreign agent such as serum, vaccine, antigenic substance or organism. "Pro-apoptotic molecules XAF1, BID, cyto c, CASP10, AIFM2, were significantly up-regulated after infection with N-PRRSV, which may induce apoptosis of virus-infected cells." (PMID 20614006, 2010).
cardiac diseases (1 paper, 2025). "Accordingly, the AIFM2 pathway was reported as one of the mitochondrial pathways linked to ferroptosis in cardiac diseases." (PMID 41008965, 2025).
hematological malignancies (1 paper, 2023). "However, it’s noteworthy that there are limited studies targeting GPX4 and AIFM2 in hematological malignancies to date." (PMID 38032290, 2023).
AIFM2 also shares sentences with these, for which no sentence is quoted: epithelial ovarian cancer (3 papers); Aortic dissection (2); colorectal cancer (2); glioma (2); lung adenocarcinoma (2); acute kidney injury (1); Alzheimer disease (1); Arthritis (1); asthma (1); cholangiocarcinoma (1); colitis (1); cyst (1); endometrial cancer (1); esophageal squamous cell carcinoma (1); glioblastoma (1); iron metabolism disorders (1); Kidney Chromophobe (1); lymphoma (1); metastatic melanoma (1); non-alcoholic fatty liver disease (1); Obesity (1); osteosarcoma (1); ovarian cancer (1); pancreatitis (1); renal carcinoma (1); spinal cord injury (1); Stomach adenocarcinoma (1); Stroke (1); thyroid cancer (1); uterine corpus endometrial carcinoma (1).
A further 1 disease shares a sentence with AIFM2 in 1 paper.